ATF4 (activating transcription factor 4)
Diseases named in the same sentence as ATF4 in open-access papers (continued):
Sharing a sentence is not in itself a finding about the gene and the disease.
infection (continued). "Therefore, the influence of PCV2 and PRV coinfection on ER activation, especially the role of GRP78 (HSPA5), eIF2α, and ATF4 in the infection, will be verified in the follow-up research." (PMID 35562870, 2022). "Infection promotes PERK activity—as measured by ATF4 levels—maximally at 48 to 96 hpi." (PMID 33947752, 2021). "To extend these observations, we examined the effect of infection on an ATF4/ATF-4 reporter gene." (PMID 34166401, 2021). "Moreover, ATF4 was found to co-localize very well with PRRSV nsp2 and nsp9, which are key components of viral replication and transcription complexes (RTCs), suggesting that ATF4 is hijacked to viral RTCs during infection." (PMID 31738790, 2019). "We provide evidence that the virus targets the UPR central regulator GRP78 for proteasomal degradation via a mechanism that requires viral glycoprotein GP2a, while both IRE1-XBP1s and PERK-eIF2α-ATF4 signaling branches of the UPR are turned on at early stage of infection." (PMID 31738790, 2019). "Moreover, consistent with results from ectopic expression studies, Rh159 does not appear to activate the UPR to the same extent as UL148, as evidenced by lower levels of phospho-eIF2α and ATF4 during TB_159HA infection." (PMID 31822584, 2019). "To determine whether ATF4 promotes L. amazonensis infection by inducing oxidative stress defense, we evaluated the role of ATF4 in controlling the oxidative stress response during infection." (PMID 29213084, 2017). "D39 interaction up-regulated expression in PMC for the gene encoding the diazepam binding inhibitor protein, which has a role in increasing host cell numbers and increased expression of the CNOT6 and ATF4 genes has been reported to be important for protecting cells from infection stress and death." (PMID 26566142, 2015). "To assess whether the effect of ATF4 knockdown on Cdc42 occurs at the transcriptional level, we measured Cdc42 transcript levels by q-PCR at various times after infection with control and shATF4 lentivirus." (PMID 25071442, 2014). "Thus, ATF4 activation regulates mtDNA levels during infection and infection-independent stress." (PMID 40811546, 2025). "Thus, ATF4 maintains host mito-1C metabolism during infection." (PMID 40811546, 2025). "Notably, our findings demonstrate that PTV-GXLZ2024 infection induces eIF2α phosphorylation while concurrently reducing ATF4 expression, suggesting that the virus may inhibit ATF4 transcription and translation to prevent CHOP activation." (PMID 41012628, 2025). "Thus, mito-1C metabolism is required for ATF4 to increase mtDNA levels during infection." (PMID 40811546, 2025). "Therefore, it can be hypothesised that the poor upregulation of ATF4 at 8 hpi may have been involved in the downregulation of the CHOP transcript at early times of infection." (PMID 39772156, 2024). "Interestingly, genotype A rt269L, generated by site-directed mutagenesis, showed enhanced autophagy induction, suggesting that polymerase with rt269L distinct in genotype C infection could play a key role in PERK–eIF2α–ATF4 axis-mediated autophagy induction." (PMID 36997871, 2023). "Interestingly, the expression of the DDIT3 (DNA damage-inducible transcript 3) gene, coding for the C/EBP homologous protein (CHOP), which is involved in the unfolded protein response downstream to ATF4, was significantly higher at 9 h post-infection compared to the previous time points." (PMID 36768954, 2023). "To determine how PD linked DJ-1 mutations affect ATF4 protein expression under basal and ER stress conditions, we infected cortical neurons and SH-SY5Y+ cells with recombinant-adenovirus-expressing Flag-DJ-1 WT, Flag-DJ-1 L166P, or pcDNA3 (empty vector) as a control for 30 h following infection." (PMID 30755590, 2019). "Importantly, ATF4 levels were increased in corneas, compared to controls in mouse A. fumigatus keratitis models developed by intrastromal injection or corneal epithelium scratch 3 days after infection." (PMID 30647960, 2018).
infection (continued). "To understand the activation of UPR by any of these pathways, we used confocal microscopy and quantified the translocation of downstream transcription factors, such as XBP1, ATF4, and ATF6, inside the nucleus upon infection." (PMID 40272166, 2025). "Infection with G. parasuis at MOIs of 10 and 100 led to a significant upregulation of CHOP, ATF4, p-PERK, p-eIF2α, eIF2α, and p-JNK levels compared to the control group (p < 0.05)." (PMID 40665414, 2025). "Because infection induced the expression of TFAM and TWNK, we posited that ATF4 regulated mtDNA levels in a TFAM- and TWNK-dependent manner." (PMID 40811546, 2025). "Post-infection, members of the heat shock protein 70 (HSP70) family, specifically HSPA1B, and transcription factors ATF4, DDIT3, and JUNB showed increased expression (p < 0.05)." (PMID 39600797, 2024). "Our data revealed that genotype C rt269L versus rt269I infection led to improved mitochondrial dynamics and enhanced autophagic flux, mainly due to the activation of the PERK–eIF2α–ATF4 axis." (PMID 36997871, 2023). "Relative to Adv-GFP, either Adv-ATF4 or Adv-NRF2 induced Slc7a11 mRNA in WT and Atf4Δ hepatocytes, but the response to Adv-ATF4 was suppressed in Nfe2l2−/− hepatocytes, a defect that was overcome by Adv-NRF2 infection." (PMID 36996941, 2023). "In this light, increased GAS5, TBL2, ATF4, and DDIT3 would be explained as related to cell stress upon infection." (PMID 36768954, 2023). "We found cytokines like IFNγ, IL-4, IL-13, IFNβ1, TNFα, and transcriptional regulators such as HIF1α, STAT1, CTCF, TP73, IRF1, MXD1, ATF4, SPI1 mediate macrophage activation upon infection." (PMID 35789215, 2022). "We studied expression profiles of molecules like phosphorylated-IRE1-α (p-IRE1-α), total-IRE1-α phosphorylated-PERK (p-PERK), total-PERK, ATF-4, CHOP and phosphorylated-JNK (p-JNK), total-JNK upon infection by JEV and WNV of Neuro-2A and SH-SY5Y cells." (PMID 35727063, 2022). "Three out of fourteen genes (ATF4, CHOP, and GADD45A) involved in the activation of the PERK pathway during ER stress were upregulated after P150 infection compared to P1." (PMID 35992665, 2022). "After infection for 4 h, the expressions of GRP78, EIF2α, P-EIF2α, and ATF4 were markedly increased, and those of ATF6 and P-IRE1α showed no significant changes." (PMID 35327108, 2022). "Taking this into account, transcriptomic analysis resulted in an increase in XBP1, IRE1α, CHOP, ATF6, ATF4, PERK, EIF2α and BIP expression after infection with NOX5-β adenovirus at all time conditions." (PMID 33572841, 2021). "Our results found that the expression of ER stress marker genes ATF4, CHOP, and CHAC1 were up-regulated in Ms_Rv0580c infected THP-1 macrophages as compared to Ms_pNIT infected THP-1 macrophages, at 24 h post-infection." (PMID 33535567, 2021). "As eIF2α-ATF4 pathway has been previously proposed to regulate stress or infection-induced expression of autophagy pathway genes, we first questioned if HRI engages the eIF2α-ATF4 signaling axis when the UPS is blocked." (PMID 33168630, 2021). "The data indicate that upregulation and nuclear translocation of both ATF4 and Nrf2 occur in response to WNV-infection." (PMID 28241074, 2017). "The protein kinase RNA-like endoplasmic reticulum kinase (PERK) arm of the UPR was activated, as the expression of both activating transcription factor 4 (ATF4) and CHOP (DDIT3), critical regulators of the pathway, was altered after infection." (PMID 26792742, 2016). "Contrary to our expectation, the loss of ATF4 did not block the increase in TFAM and TWNK transcripts during infection." (PMID 40811546, 2025). "As expected, infection induced MTHFD2 and SHMT2 in an ATF4-dependent manner." (PMID 40811546, 2025). "Tripathi and colleagues showed elevated levels of CHOP, ATF4 and BiP in the blood of TBM patients versus healthy individuals and in severe TBM versus mild TBM patients, suggesting that ER stress relates to the severity of infection." (PMID 40420159, 2025).
infection (continued). "Additionally, the protein levels of ATF4 and CHOP were drastically increased in the ΔespF group compared with the wild-type group, suggesting that infection with the espF-deletion O157:H7 strain more strongly stimulates ER stress in Caco-2 cells." (PMID 40430759, 2025). "Next, we investigated whether the PERK-mediated ATF4 and CHOP signaling pathways were activated in cardiomyocytes upon infection with cardiotropic viruses." (PMID 38664417, 2024). "Additionally, our data showed that cp BVDV strongly induced CHOP expression via ATF4, whereas ncp BVDV showed weak induction of CHOP during infection." (PMID 36939351, 2023). "Our data showed that, compared with the rt269I type, the rt269L type, which presented exclusively in HBV genotype C infection, leads to improved mitochondrial dynamics or bioenergetics, mainly due to autophagy induction via activation of the PERK–eIF2α–ATF4 axis in an HBx protein-dependent manner." (PMID 36997871, 2023). "After infection of 2 h, the expressions of ATF4 and P-EIF2α were increased; however, that of GRP78 was not changed." (PMID 35327108, 2022). "Deletion of GCN2 or its downstream effector ATF4 in MEF cells significantly lowered the induction of CAT1 mRNA upon infection with Toxoplasma, with no change in protein levels." (PMID 31194856, 2019). "Following infection of GCN2-/- cells, there was a significant delay in the induction of host eIF2α-P, with appreciable levels detected only after 18 hours post-infection (hpi) that was accompanied by a delay in the induction of ATF4 mRNA levels." (PMID 31194856, 2019). "While PERK-/- cells showed robust eIF2α-P early in infection along with a rise in ATF4 mRNA levels starting at 2 hpi, eIF2α-P was detected in the combined GCN2-/-PERK-/- cells only after 24 hpi, followed by an increase in ATF4 mRNA levels at 36 hpi." (PMID 31194856, 2019). "Although the level of eIF2α phosphorylation induced by WNV-infection is sufficient to activate ATF4 translation, it is not sufficient to induce SG formation." (PMID 28241074, 2017). "In either ATF4 or Nrf2 siRNA-transfected cells, the number of SG-positive cells increased after WNV-infection and the number of SG-positive cells further increased with both WNV-infection and Ars-treatment." (PMID 28241074, 2017). "As in the case of wild-type ATF4 over-expression, infection with the rescue construct did not further increase RhoGDIα levels above those under the control conditions." (PMID 27841340, 2016). "While Cdc42 protein decreased along with the duration of infection, there was no significant change in Cdc42 mRNA levels in cortical or hippocampal (data not shown) neurons after ATF4 knockdown." (PMID 25071442, 2014). "Infection with ΔcpsII parasites led to ATF4 activation, but unlike in the case of WT parasites, failed to drive the increases in M+2 dTMP and M+2 dTTP observed in ATF4 KO cells." (PMID 40811546, 2025). "It showed inhibition of DENV2 (EC50 = 0.82 μM) infection mainly independent of ATF4." (PMID 34957305, 2021). "However, unlike our observations in KSHV lytic infection, PERK causes ISR activation and normal ATF4 accumulation during HCMV lytic replication." (PMID 31790507, 2019). "Further evidence supporting the association of ATF4 with the replication machinery of PRRSV includes its interaction with viral RNA in pulldown assays and co-localization with negative-strand RNAs during infection." (PMID 31738790, 2019). "As for proliferation, the absence of ATF4 consecutive to the infection with Atf4-shRNA enables control cells to slightly proliferate after 5 and 7 days in 2% medium whereas the number of cells significantly decreases after infection with the control shRNA." (PMID 28460466, 2017).
infection (continued). "Infection of the hepatocyte sub-line Huh7.5.1 with JFH1 (2a) induced an acute ER stress peaking at 2–5 days post-infection (dpi), concomitant with phosphorylation of IRE1, eIF2α, and JNK, XBP1 splicing, ATF6 cleavage and upregulation of GADD34, ERdj4, P58IPK, ATF3, ATF4, and CHOP." (PMID 24904547, 2014). "However, during infection with any of the three viruses, with or without the presence of p-eIF2α, ATF4 could not be detected at any timepoint." (PMID 39861909, 2025). "Thus, a growing number of studies implicate ATF4 and ATF5 in the regulation of the immune response and reveal how the dialogue between stress responses and immune pathways can be fundamental for the regulation of tissue homeostasis by the cell in response to infection." (PMID 38534416, 2024). "Hence, our study points to a possibility that plants might possess a translational derepression pathway involving AtGCN2, eIF2α, and TBF1 that is triggered during pathogen infection and reminiscent of the yeast GCN2-eIF2α-GCN4 and mammalian GCN2/PERK-eIF2α-ATF4 pathways." (PMID 31428690, 2019). "Consistent with cytoplasmic retention, the canonical ATF4-target genes GADD34 and ASNS were not upregulated during infection as compared with the mock or TG-treated cells." (PMID 31738790, 2019). "Interestingly, only EDEM1, which is involved in the clearance of misfolded proteins, was transiently up-regulated at day 1 and day 2 post-infection, whereas BiP, DDIT3 and ATF4 mRNA expression were not affected." (PMID 34224022, 2021). "Furthermore, we found a substantial increase in ATF4 accumulation following treatment with tunicamycin (data not shown), inducing the unfolded protein response accompanied by phosphorylation of PERK and eIF2α, suggesting that the infection induces only a moderate translation arrest." (PMID 28202752, 2017).
neurodegenerative disease (22 papers, 2013 to 2026). A disorder of the central nervous system characterized by gradual and progressive loss of neural tissue and neurologic function. "In neurons and glial cells, ATF4 is a key prodeath transcriptional activator and overexpression of ATF4 is associated with retina and brain degeneration in murine models." (PMID 40338234, 2025). "This review aims to synthesize the role of ATF4 in metabolic dysfunction, neurodegenerative diseases, and ocular pathology; the mechanisms underlying its protective versus pathologic effects; and future directions to refine ATF4's potential as a clinical therapeutic target across different diseases." (PMID 41892328, 2026). "Previous research has established contradictory function of ATF4 in pathogenesis of neurodegenerative diseases." (PMID 39702495, 2024). "In this review article, we summarized the upstream and downstream mechanisms of ATF4 activation during mitochondrial stresses and disturbances and discuss therapeutic intervention against degenerative diseases by using Nrf2 activators." (PMID 30705506, 2019). "In this review, we summarized the latest discoveries on the role of the ATF4 protein in various retinal and neurodegenerative diseases." (PMID 29326555, 2017). "ATF4 is responsible for the gene regulation of molecular chaperones and proteins involved in autophagy processes and is able to trigger both pro-survival and pro-death pathways in neurodegenerative diseases." (PMID 38203652, 2023). "The increase in P-eIF2α and ATF4 has been observed in many neurodegenerative diseases." (PMID 36212697, 2022). "To date, the function of the ISR in neurodegenerative diseases has been attributed largely to the emergence of alternative translation pathways and to ATF4 transcriptional activity that drives expression of cytoplasmic chaperones and balances cell survival and cell death." (PMID 35758650, 2022). "Although CA induction of CHOP was not affected by Nrf2 knockdown in U373MG cells, cross talk between Nrf2 and ATF4 may determine cell fate during therapeutic Nrf2 activation within many degenerative diseases." (PMID 30959808, 2019). "ATF4 has distinct effects in different models of neurodegenerative diseases." (PMID 23874395, 2013). "Given the role of ATF4 as part of the ISR and the relevance of the ISR in neurodegenerative diseases, we wondered if ISR activation is a consequence of IGHMBP2 deletion." (PMID 38803225, 2024). "WFS1 is a negative regulator of ER stress, a key event involved in the onset of neurodegenerative diseases, by preventing ATF6 activation thereby blocking the expression of proteins (CHOP, ATF4, BIP, and sXBP1) that promote cellular apoptosis." (PMID 36890518, 2023).
metabolic disease (10 papers, 2012 to 2026). A congenital disorder (due to inherited enzyme abnormality) or acquired (due to failure of a metabolically important organ) disorder resulting from an abnormal metabolic process. "As ATF4 is known to have causal effects in the progression of various neurodegenerative or metabolic diseases, this tool may facilitate the study of ATF4 function in Drosophila models of human diseases." (PMID 25978358, 2015). "The soy protein β-conglycinin is a good example of an ATF4 activator that can prevent metabolic disorders through the induction of FGF21 without ER stress." (PMID 35159314, 2022).